RNVU1-15 (RNA, variant U1 small nuclear 15)
Synonyms: vU1.15; RNU1-66; vU1.16; RNU1-121; RNVU1-16
Gene: Small nuclear RNA gene on chromosome 1 (144,412,576 to 144,412,740, forward strand). Ensembl gene ENSG00000207205.
Gene Ontology:
Molecular function: pre-mRNA 5'-splice site binding
Biological process: mRNA 5'-splice site recognition
Cellular component: U1 snRNP
Homologues: Paralogues in human: RNU1-1 (89% identical), RNU1-2 (89% identical), RNU1-27P (89% identical), RNU1-28P (89% identical), RNU1-3 (89% identical), RNU1-4 (89% identical), RNVU1-18 (89% identical), RNVU1-29 (89% identical), U1 (89% identical), RNVU1-28 (88% identical), RNVU1-7 (88% identical), RNVU1-19 (88% identical), and 133 more.